MEN1 (menin 1)
Diseases named in the same sentence as MEN1 in open-access papers (continued):
Sharing a sentence is not in itself a finding about the gene and the disease.
multiple endocrine neoplasia type 1 (continued). "Genetics: Inactivating mutation of the MEN1 gene, located on chromosome 11q13, was first reported in 1997, but the phenotype of MEN1 syndrome was first noted in a patient with acromegaly and enlarged parathyroid glands by Erdheim in 1903." (PMID 33805450, 2021). "Heterozygous Men1 mutation, on the other hand, recapitulates the autosomal dominant nature of familial MEN1 syndrome." (PMID 34680266, 2021). "BACKGROUND: Multiple endocrine neoplasia type 1 (MEN 1) is a rare autosomal dominant disorder caused by mutations in the MEN1 gene, which encodes the menin protein." (PMID 35018761, 2021). "Although PPomas often occur sporadically, they have been associated with multiple endocrine neoplasia type 1 (MEN1)." (PMID 34118524, 2021). "MEN1 syndrome is caused by germinal heterozygote inactivating mutation of the MEN1 gene, encoding the menin tumor suppressor protein." (PMID 33919851, 2021). "Most cases of multiple endocrine neoplasia type 1 occur in a familial setting; however, in 10% of patients, de novo variants have been described and single reports of mosaic MEN1 alterations have been noted." (PMID 33807230, 2021). "Nine patients were diagnosed with multiple endocrine neoplasia type 1 (MEN1) in which all the associated functional PanNENs were insulinomas." (PMID 33204258, 2020). "The MEN1 gene is known to be causative for multiple endocrine neoplasia type 1, which undergoes frequent LOH and mutation in PanNETs." (PMID 32521808, 2020). "Multiple endocrine neoplasia type 1 (MEN1) is an autosomal dominant disorder caused by mutations of the tumor suppressor gene MEN1." (PMID 32715270, 2020). "After counselling, the patient agreed to undergo genetic analysis which revealed MEN1 missense mutations (NM_130799: c.1256G > T p.(Gly419Val)) on chromosome 11 (Chr11:g.64572600C > A) causing multiple endocrine neoplasia type 1 (MEN1) syndrome." (PMID 31797261, 2020). "Classical tumor predisposition syndromes include multiple endocrine neoplasia type 1 (MEN1) and type 4 (MEN4) syndromes, Carney complex, and X-LAG syndromes." (PMID 33574795, 2020). "Multiple endocrine neoplasia type 1 (MEN1), an autosomal dominant disorder caused by MEN1 germline mutations, is characterised by parathyroid, pancreatic and pituitary tumours." (PMID 32348957, 2020). "Germline MEN1 mutations result in multiple endocrine neoplasia type 1, a tumor predisposition syndrome." (PMID 32384699, 2020). "Pathogenic variants in the MEN1 gene cause multiple endocrine neoplasia type 1 (MEN1), an autosomal dominant disorder in which patients develop neoplastic lesions in various endocrine tissues, principally the parathyroids, pituitary, and pancreas." (PMID 31737856, 2019). "Two patients were known cases of Multiple Endocrine Neoplasia type 1 (MEN1), one was known to harbour a pathogenic MEN1 variant." (PMID 31592449, 2019). "Multiple endocrine neoplasia type 1 is a rare tumor syndrome caused by germline mutations of MEN1 gene." (PMID 31044390, 2019). "Although MNX1 functions as an oncogene to promote pancreatic islet cell tumors in multiple endocrine neoplasia type 1 (MEN1), this particular mutation is common in the population and unlikely to be relevant to predisposition." (PMID 29440180, 2018). "Multiple endocrine neoplasia type 1 (MEN1) is an endocrine tumor syndrome caused by heterozygous mutations in the MEN1 tumor suppressor gene." (PMID 29335487, 2018). "Heterozygous germline mutation of the MEN1 tumor suppressor gene is responsible for multiple endocrine neoplasia type 1." (PMID 29416715, 2018). "Although mutations in the MEN1 gene are rare, they represent important objects of screening as they provide the means of early diagnostics of MEN1 syndrome." (PMID 28187001, 2017). "The tumor suppressor MEN1 gene, located on chromosome 11q13 and encoding for menin, is lost in tumors of MEN1 syndrome and in about 30% of sporadic parathyroid adenomas." (PMID 28157158, 2017).
multiple endocrine neoplasia type 1 (continued). "Mutations to the MEN1 gene, which encodes the Menin protein, are responsible for multiple endocrine neoplasia syndrome, type 1 (MEN1), an example of a hereditary cancer." (PMID 27011205, 2016). "MEN1 syndrome associated PanNETs show loss of the wild-type MEN1 allele in up to 100 % of cases (compared to 19–44 % in sporadic PanNETs)." (PMID 27267993, 2016). "Germline heterozygous loss-of-function mutations of the tumor suppressor MEN1 gene – the main molecular defect causing the MEN1 syndrome – have been detected in about 70–80% and 30% of patients with familial and sporadic MEN1 respectively." (PMID 25416039, 2015). "For example, the MEN1 gene encodes menin, an integral subunit of MLL1 and MLL2, and is mutated in patients with multiple endocrine neoplasia type 1 (MEN1)." (PMID 26147337, 2015). "In the present study the germline mutational analysis revealed a frameshift mutation in exon 3 of the MEN1 gene, which is a known mutation of the MEN1 gene associated with MEN1 syndrome." (PMID 24959251, 2014). "Menin, a protein encoded by the MEN1 gene, is mutated in patients with multiple endocrine neoplasia type 1 (MEN1)." (PMID 25594065, 2014). "Multiple endocrine neoplasia type 1 (MEN1) is an autosomal dominant familial disorder with mutations in the tumor suppressor gene MEN1." (PMID 25136513, 2014). "Menin (MEN1) is the product of the tumor suppressor gene MEN1 that is mutated in the inherited syndrome multiple endocrine neoplasia type 1." (PMID 22240255, 2012). "The tumor suppressor menin (MEN1) is mutated in the inherited disease multiple endocrine neoplasia type I, and has several documented cellular roles, including the activation and repression of transcription effected by several transcription factors." (PMID 22240255, 2012). "The association of exon 2 mutation of the MEN1 gene with bilateral adrenal carcinomas in MEN1 syndrome, should be further investigated." (PMID 21266030, 2011). "Mutations of the MEN1 gene predispose patients to multiple endocrine neoplasia type 1 (MEN1), characterised by the occurrence of multiple endocrine tumours affecting mainly the parathyroid glands, the endocrine pancreas and the anterior pituitary." (PMID 20663219, 2010). "Exploring tumor-preventive strategies may be particularly relevant for inherited cancer syndromes with high tumor penetrance such as pancreatic neuroendocrine tumors (PNETs) associated with multiple endocrine neoplasia type 1 (MEN1)." (PMID 41883001, 2026). "Multiple endocrine neoplasia type 1 (MEN1) is a rare hereditary tumor syndrome caused by inactivating mutations of the MEN1 gene and characterized by the occurrence of multiple endocrine tumors within a single patient (i.e., parathyroid, pituitary, and pancreatic neuroendocrine tumors (NETs))." (PMID 40507887, 2025). "However, resistance associated with Multiple Endocrine Neoplasia type 1 (MEN1) mutations remains a challenge." (PMID 41155189, 2025). "Moreover, Men1 is responsible for multiple endocrine neoplasia type 1 (MEN1), a hereditary disorder causing tumours in several endocrine glands, including the pancreas as well as the parathyroid and pituitary glands." (PMID 38731926, 2024). "Notably, three pathogenic germline variants (PGVs) in MEN1 that are frequently observed in MEN1 syndrome abolish the upregulation of BRCA1, RAD51, and RAD51AP1 and consequently abolish menin’s ability to promote DNA double-strand break repair." (PMID 39336822, 2024). "The following keywords have been used: parathyroid tumorigenesis; parathyroid tumors; multiple endocrine neoplasia type 1 syndrome (MEN1); MEN1 gene; allelic loss; loss of heterozygosity; MEN1 parathyroid tumors; tumor suppressor genes; oncogenes; epigenetics; oncomir; microRNAs/miRNAs." (PMID 39519139, 2024).
multiple endocrine neoplasia type 1 (continued). "The study of parathyroid tumorigenesis associated with multiple endocrine neoplasia type 1 syndrome (MEN1) represents an excellent paradigm for understanding genetic–epigenetic–molecular aspects underlying the pathophysiology of PHPT, both in relation to the syndromic and non-syndromic forms." (PMID 39519139, 2024). "Primary HPT is common to both MEN1, or Wermer’s syndrome (with associated tumors of the pituitary gland, endocrine pancreas and digestive tract) and MEN2A, or Sipple’s syndrome (with associated pheochromocytoma and medullary thyroid cancer) and the recently describe MEN4." (PMID 38622315, 2024). "Menin is encoded by the MEN1 gene and constitutional loss of its tumor suppressor function may lead to endocrine hyperplasia or neoplasms known as the multiple endocrine neoplasia type 1 syndrome." (PMID 38174649, 2023). "On the other hand, primary hyperparathyroidism may embrace associations with other types of adrenal tumors as seen in multiple endocrine neoplasia type 1 and 2 underlying well known pathogenic variants of MEN1 and RET." (PMID 38139166, 2023). "Multiple endocrine neoplasia type-1 (MEN1) is a rare endocrine syndrome, associated with MEN1 pathogenic variants, inherited by autosomal dominant manner, and characterized by the occurrence of primary hyperparathyroidism, pituitary adenoma, and pancreatic neuroendocrine tumors (NETs)." (PMID 35407574, 2022). "MEN1 syndrome is the result of a germline mutation of the MEN1 tumor suppressor gene." (PMID 34681263, 2021). "MEN1 syndrome is caused by a germline mutation in the MEN1 gene, a tumor suppressor." (PMID 34118524, 2021). "Indeed, the MEN1 gene is largely known as a tumor suppressor in several types of endocrine tissues, since its mutation predisposes patients to multiple endocrine neoplasia type 1 syndrome (MEN1 syndrome, OMIM 131100)." (PMID 34446068, 2021). "They suggest that the p27 tumor suppressor gene could represent a disease modifier gene in MEN1 syndrome cases associated with MEN1 germline mutations." (PMID 33312161, 2020). "Moreover, MEN1 patients with high-impact MEN1 mutations were more likely to develop GEP-NETs revealing an interesting geno-phenotypic association in MEN1 syndrome with potential prognostic consequences regarding genetic counseling." (PMID 31044390, 2019). "Germline MEN1 mutations have also been noted in families with a parathyroid only disorder, familial isolated primary hyperparathyroidism, where there is a higher frequency of missense mutations compared to patients with the MEN1 syndrome." (PMID 31263451, 2019). "MEN1 mutation analysis was performed in all patients with clinical suspicion of MEN1 syndrome." (PMID 31044390, 2019). "MEN1 gene mutations detected in 54 probands with MEN1 syndrome." (PMID 29036195, 2017). "Multiple endocrine neoplasia type 1 (MEN1) syndrome results from mutations in the MEN1 gene and causes tumor formation via largely unknown mechanisms." (PMID 26871472, 2016). "Insulinomas, which are rare tumors causing hyperinsulinemic hypoglycemia are usually sporadic but may also occur in association with multiple endocrine neoplasia type 1 (MEN-1) syndrome an autosomal dominant disorder caused by MEN1 gene mutations." (PMID 26307114, 2015). "Germline genetic alterations in MEN1 (multiple endocrine neoplasia type 1) gene are associated with PHPT in the context of MEN1 syndrome, and mutations in HRPT2 (hyperparathyroidism 2) gene are associated with HPT-JT (Hyperparathyroidism-Jaw tumor) familial syndrome." (PMID 22567348, 2011). "Mutations of the MEN1 gene predispose to multiple endocrine neoplasia type 1 (MEN1) syndrome." (PMID 20663219, 2010).
multiple endocrine neoplasia type 1 (continued). "Multiple endocrine neoplasia type 1 (MEN1) is a rare syndrome caused by inactivating mutations in the MEN1 tumor suppressor gene." (PMID 38892509, 2024). "Notably, one patient with an APC gene mutation also harbored a SMAD4 (SMAD family member 4) gene mutation, while another patient with a SMAD4 gene mutation (n = 2, 14.29%) concurrently presented with a MEN1 (Multiple Endocrine Neoplasia Type 1) mutation (n = 1, 7.14%)." (PMID 39162366, 2024). "Interestingly, clinical data in individuals with MEN1 syndrome suggest that MEN1 patients may be at increased risk of developing breast cancer." (PMID 39336822, 2024). "In conclusion, it is essential to underline the importance of managing MEN1 patients through a multidisciplinary approach, which should include also the figure of the nutritionist/dietitian, a specific aspect that is currently missing in the global management of MEN1 syndrome." (PMID 38892509, 2024). "MEN1 is a regulator of gene transcription and germline deficiencies are causatively associated with developing Multiple Endocrine Neoplasia Type 1 (MEN1), which is a rare, hereditary tumour condition." (PMID 36883553, 2023). "Finally, parathyroid tumors from 2 patients with clinical suspicion of MEN1 syndrome and inconclusive genetic results due to MEN1 gene variants of unknown significance were analyzed by menin immunohistochemistry and for LOH of MEN1 using SNP-array." (PMID 37199453, 2023). "In addition, either the presence of MEN-1 (Multiple Endocrine Neoplasia-type 1) mutations, or mutations of DAXX (death-domain-associated protein) or ATRX (alpha thalassemia/mental retardation syndrome X-linked), did not improve OS with everolimus treatment (p = 0.34)." (PMID 35267558, 2022). "Inheritance of germline mutations in one MEN1 allele from either parent leads to a familial autosomal dominant tumor syndrome called multiple endocrine neoplasia type 1 (MEN 1)." (PMID 34680266, 2021). "Among patients with the rare diagnosis of pancreatic neuroendocrine tumor (P-NET), a substantial proportion suffer from the inherited cancer syndrome multiple endocrine neoplasia type 1 (MEN1), which is caused by germline mutations of the MEN1 suppressor gene." (PMID 32884006, 2020). "Multiple Endocrine Neoplasia type 1 (MEN1) is diagnosed when two out of the three primary MEN1-associated endocrine tumors occur in a patient." (PMID 27842554, 2016). "Lipoma in patients with the multiple endocrine neoplasia type 1 (MEN1) syndrome is a type of benign fat-cell tumor that has biallelic inactivation of MEN1 that encodes menin and could serve as a model to investigate normal and pathologic fat-cell (adipocyte) proliferation and function." (PMID 26229531, 2015). "Germline inactivating mutations of MEN1 gene are the main cause of multiple endocrine neoplasia type 1 (MEN1), a syndrome characterized by tumors in the pituitary gland, the parathyroid glands, and the enteropancreatic neuroendocrine tissues." (PMID 25132853, 2014). "Menin is a nuclear protein encoded by the Men1 gene, which is mutated in familial multiple endocrine neoplasia type 1 (MEN1) patients." (PMID 21318185, 2010). "Multiple endocrine neoplasia type 1 syndrome (MEN1, OMIM #131100) is a rare autosomal dominant disorder." (PMID 39826015, 2025). "The heritable causes of PHPT comprise 10% to 15%, with the most common forms being multiple endocrine neoplasia type 1 (MEN1) and type 2 (MEN2)." (PMID 40115416, 2025). "The most common genetic disorders resulting in hyperparathyroidism include multiple endocrine neoplasia type 1 (Wermer’s syndrome, MEN1) and type 2A (MEN2A), hyperparathyroidism–jaw tumor (HPT-JT) syndrome, familial isolated hyperparathyroidism (FIHP)." (PMID 40149408, 2025). "There was one case each of multiple endocrine neoplasia type 1 (MEN1) and Von Hippel–Lindau (VHL) syndrome, as well as one functional NET (insulinoma)." (PMID 40768514, 2025).
multiple endocrine neoplasia type 1 (continued). "The significant difference in serum values of miR-24-3p between MEN1 patients and healthy subjects seems to indicate that this circulating miRNA as a possible additional biochemical marker in the diagnosis of MEN1 syndrome." (PMID 40507887, 2025). "SDHB mutations were documented in five of the nine phaeochromocytoma and paraganglioma patients, and patient with an insulinoma had multiple endocrine neoplasia type 1 (MEN1)." (PMID 40272497, 2025). "PNETS are a common finding in individuals with hereditary conditions such as multiple endocrine neoplasia syndrome type 1 (MEN1), von Hippel-Lindau disease (VHL), neurofibromatosis type 1 (NF1), and tuberous sclerosis (TSC)." (PMID 40901227, 2025). "This progress report will outline current insights into surveillance and management of the major clinical manifestation of MEN1 syndrome in children and adults with MEN1 diagnosis." (PMID 39826015, 2025). "The MEN1 gene was first discovered in the context of multiple endocrine neoplasia type 1 (MEN1) syndrome, where it functions as a potent tumor suppressor gene." (PMID 39336822, 2024). "In our literature review, they are generally found in cases with the syndrome, multiple endocrine neoplasia type 1 (MEN1)." (PMID 39156287, 2024). "MEN1, also known as Wermer’s syndrome (OMIM *131100), is an autosomal dominant syndrome with a worldwide prevalence of 3–20 in 100,000 individuals and a high penetrance due to mutations in the MEN1 gene." (PMID 39336996, 2024). "The mean age at diagnosis was 60 years, though significantly earlier in patients with multiple endocrine neoplasia type 1 (MEN1)." (PMID 38785751, 2024). "In selected cases (patients aged\30 years at diagnosis, family history of hypercalcemia, neuroendocrine tumours), assessing the presence of a familial syndrome (Multiple Endocrine Neoplasia 1––MEN1, MEN2A, Hyperparathyroidism." (PMID 38622315, 2024). "BACKGROUND: Multiple endocrine neoplasia type 1 (MEN1) — is a rare syndrome with an autosomal dominant inheritance pattern caused by a mutation in the tumor suppressor gene (MEN1)." (PMID 38433544, 2024). "These can be caused by germline mutations in MEN1, GNAS, or PRKAR1 leading to multiple endocrine neoplasia type I (MEN1), McCune-Albright syndrome, and Carney complex, respectively." (PMID 38479600, 2024). "Multiple endocrine neoplasia type 1 (MEN1) stands as a rare, hereditary syndrome of endocrine tumors characterized by an autosomal dominant pattern of inheritance, deriving from mutations within the MEN1 gene." (PMID 39201946, 2024). "These include Multiple Endocrine Neoplasia type 1 (MEN1) (Wermer syndrome), von Hippel–Lindau disease, neurofibromatosis 1 (NF-1) and the tuberous sclerosis complex (TSC)." (PMID 36765737, 2023). "In this regard, pHPT patients with multiple endocrine neoplasia of type-1 (MEN1) represent critical clinical candidates for accurate parathyroid diagnostic imaging with potential therapeutic implications." (PMID 37181366, 2023). "While insulinomas are usually sporadic, around 4–5% of patients with insulinomas have multiple endocrine neoplasia type 1 (MEN1)." (PMID 37623030, 2023). "In this large cohort of children with rare pediatric insulinomas, MEN1 syndrome and G2 tumors were frequent, as well as hitherto undiscovered MEN1 manifestations in family members." (PMID 37152923, 2023). "Menin immunohistochemistry is useful in the recognition of MEN1 syndrome as well as in the clinical genetic analysis of patients with inconclusive MEN1 germline testing." (PMID 37199453, 2023). "Inherited disorders associated with a relatively high incidence of PanNETs include multiple endocrine neoplasia type 1 (MEN1), von Hippel–Lindau disease, von Recklinghausen’s disease (neurofibromatosis 1), and tuberous sclerosis." (PMID 37623030, 2023). "The gene MEN1 is related to Multiple Endocrine Neoplasia Syndrome type 1, of autosomal dominant inheritance (OMIM:613733)." (PMID 37895483, 2023).